H2AC19 (H2A clustered histone 19)
Description:
Core component of nucleosome. Nucleosomes wrap and compact DNA into chromatin, limiting DNA accessibility to the cellular machineries which require DNA as a template. Histones thereby play a central role in transcription regulation, DNA repair, DNA replication and chromosomal stability. DNA accessibility is regulated via a complex set of post-translational modifications of histones, also called histone code, and nucleosome remodeling.
Synonyms: HIST2H2AA4; H2A/r
Gene: Protein-coding gene on chromosome 1 (149,851,061 to 149,851,652, forward strand). Ensembl gene ENSG00000288859.
Subcellular location: Nucleus; Chromosome
Subcellular location (Human Protein Atlas): Nucleoplasm
Pathways (Reactome):
Gene expression (Transcription): B-WICH complex positively regulates rRNA expression; DNA methylation; ERCC6 (CSB) and EHMT2 (G9a) positively regulate rRNA expression; MLL4 and MLL3 complexes regulate expression of PPARG target genes in adipogenesis and hepatic steatosis; NoRC negatively regulates rRNA expression; PRC2 methylates histones and DNA; RNA Polymerase I Promoter Escape; RNA Polymerase I Promoter Opening; RUNX1 regulates genes involved in megakaryocyte differentiation and platelet function; RUNX1 regulates transcription of genes involved in differentiation of HSCs; Regulation of endogenous retroelements by KRAB-ZFP proteins; Regulation of endogenous retroelements by Piwi-interacting RNAs (piRNAs); Regulation of endogenous retroelements by the Human Silencing Hub (HUSH) complex; SIRT1 negatively regulates rRNA expression; Transcriptional regulation by small RNAs
Chromatin organization: CHD1 and CHD2 subfamily; CHD6, CHD7, CHD8, CHD9 subfamily; ChAHP complex assembly; HATs acetylate histones; HDACs deacetylate histones; Interaction of NuRD complexes with transcription factors; NuRD complex assembly; RMTs methylate histone arginines
Cell Cycle: Condensation of Prophase Chromosomes; Deposition of new CENPA-containing nucleosomes at the centromere; Inhibition of DNA recombination at telomere; Packaging Of Telomere Ends
DNA Repair: Cleavage of the damaged purine; Cleavage of the damaged pyrimidine; Recognition and association of DNA glycosylase with site containing an affected purine; Recognition and association of DNA glycosylase with site containing an affected pyrimidine
Disease: Defective pyroptosis; Dengue Virus-Host Interactions; HCMV Early Events; HCMV Late Events
Metabolism of proteins: Amyloid fiber formation; Metalloprotease DUBs; UCH proteinases; Ub-specific processing proteases
Signal Transduction: Activated PKN1 stimulates transcription of AR (androgen receptor) regulated genes KLK2 and KLK3
and 15 more pathways
Gene Ontology:
Molecular function: protein binding; structural constituent of chromatin; DNA binding; protein heterodimerization activity
Biological process: heterochromatin formation
Cellular component: extracellular exosome; nucleoplasm; nucleus; nucleosome; chromosome
Homologues: Orthologues: chimpanzee H2AC19 (100% identical), dog H2AC19 (100% identical), mouse H2ac19 (100% identical), pig H2AC19 (100% identical), rabbit H2AC19 (100% identical), Drosophila melanogaster His2A:CG31618 (85% identical), Drosophila melanogaster His2A:CG33808 (85% identical), Drosophila melanogaster His2A:CG33814 (85% identical), Drosophila melanogaster His2A:CG33817 (85% identical), Drosophila melanogaster His2A:CG33820 (85% identical), Drosophila melanogaster His2A:CG33823 (85% identical), Drosophila melanogaster His2A:CG33826 (85% identical), and 13 more. Paralogues in human: H2AC18 (100% identical), H2AC11 (98% identical), H2AC13 (98% identical), H2AC15 (98% identical), H2AC16 (98% identical), H2AC17 (98% identical), H2AC6 (98% identical), H2AC20 (98% identical), H2AC25 (98% identical), H2AC7 (98% identical), H2AC12 (97% identical), H2AC4 (97% identical), and 15 more.
Diseases named in the same sentence as H2AC19 in open-access papers:
H2AC19 is named in the same sentence as 3 diseases in open-access papers, as found by Europe PMC text mining. Sharing a sentence is not in itself a finding about the gene and the disease. The quoted sentences say what the papers report.
tumor (1 paper, 2023). "Furthermore, we identified some potential prognostic biomarkers for HCC, a highly malignant tumor with high incidence and mortality rates, including AFP, H2AC19, KLF11, and IFNG." (PMID 37107646, 2023).
H2AC19 also shares sentences with these, for which no sentence is quoted: colorectal carcinoma (1 paper); intestinal ulcers (1).